GSE1 (Gse1 coiled-coil protein)
Synonyms: KIAA0182; CRHSP24
Tractability: PROTAC: ubiquitination databases record sites on it.
Gene: Protein-coding gene on chromosome 16 (85,169,525 to 85,676,204, forward strand). Ensembl gene ENSG00000131149.
Subcellular location (Human Protein Atlas): Mitochondria; Nucleoplasm
Gene Ontology:
Molecular function: protein binding
Genetic constraint (gnomAD): Loss-of-function variants: 20 observed, 81.64 expected, observed/expected ratio (o/e) 0.24, 90% interval 0.17 to 0.36. The synonymous counts are far from expectation, so gnomAD's model fits this gene poorly and the ratio says little. Missense variants: 2,113 observed, 1,526.5 expected, observed/expected ratio (o/e) 1.38, 90% interval 1.34 to 1.43. Synonymous variants: 1,013 observed, 670.66 expected, observed/expected ratio (o/e) 1.51, 90% interval 1.43 to 1.59.
Homologues: Orthologues: chimpanzee GSE1 (99% identical), macaque GSE1 (98% identical), dog GSE1 (91% identical), mouse Gse1 (90% identical), rat Gse1 (90% identical), pig GSE1 (89% identical), guinea pig GSE1 (87% identical), tropical clawed frog gse1 (66% identical), zebrafish gse1b (58% identical).
Diseases named in the same sentence as GSE1 in open-access papers:
GSE1 is named in the same sentence as 7 diseases in open-access papers, as found by Europe PMC text mining. Sharing a sentence is not in itself a finding about the gene and the disease. The quoted sentences say what the papers report.
breast carcinoma (3 papers, 2007 to 2021). "Our finding is, in part, corroborated by a recent report that the oncoprotein GSE1 is aberrantly expressed in breast cancer and implicated in the proliferation, migration, and invasion of breast cancer cells." (PMID 34439112, 2021). "GSE1, also known as KIAA0182, has been shown to possess oncogenic properties in human breast cancer cells and gastric cancer and accelerates tumorigenesis in neuroepithelial stem cells of Gorlin syndrome patients, who are predisposed to medulloblastoma due to PTCH1 mutation." (PMID 31470906, 2019). "GSE1 (genetic suppressor element 1), a proline-rich protein, also known as KIAA0182, was found in two WHO°I IVMs and has been shown to possess oncogenic properties in human breast cancer cells, gastric cancer and in neuroepithelial stem cells." (PMID 31470906, 2019).
gastric cancer (3 papers, 2019 to 2021). A primary or metastatic malignant neoplasm involving the stomach. "In this study, we reported human Gse1 coiled-coil protein (GSE1) promoted trastuzumab resistance in HER2-positive gastric cancer cells." (PMID 33623790, 2021).
medulloblastoma (3 papers, 2019 to 2021). A malignant, invasive embryonal neoplasm arising from the cerebellum. "From these analyses, we conclude that mutant DDX3X and loss of GSE1 act as drivers of SHH medulloblastoma tumorigenesis, while mutations in KDM3B may represent a passenger." (PMID 31204176, 2019).
meningioma (1 paper, 2019). A generally slow growing tumor attached to the dura mater. "Taken together, APC, KDR and GSE1 mutations might contribute to meningioma growth, however, validation by Sanger sequencing and functional analyses are needed to strengthen these preliminary findings." (PMID 31470906, 2019).
tumor (4 papers, 2014 to 2025). "Specifically, PIWIL4, SATB1, GSE1, NCOR1, SAP30L, ATM, and BMI1 were significantly downregulated in tumor tissues relative to normal controls, while BUB1, CHEK1, MASTL, DNAJC2, UBE2D1, and SSRP1 showed pronounced upregulation." (PMID 41208974, 2025).
GSE1 also shares sentences with these, for which no sentence is quoted: prostate carcinoma (2 papers); Gorlin syndrome (1).